LCE3A (late cornified envelope 3A)
Description:
A structural component of the cornified envelope of the stratum corneum involved in innate cutaneous host defense (Probable). Possesses defensin-like antimicrobial activity against a broad spectrum of Gram-positive and Gram-negative bacteria, both aerobic and anaerobic species. Upon inflammation, may regulate skin barrier repair by shaping cutaneous microbiota composition and immune response to bacterial antigens.
Synonyms: LEP13
Tractability: No criterion of Open Targets' tractability assessment is met for any kind of drug.
Gene: Protein-coding gene on chromosome 1 (152,622,834 to 152,623,103, reverse strand). Ensembl gene ENSG00000185962.
Pathways (Reactome):
Developmental Biology: Formation of the cornified envelope
Gene Ontology:
Molecular function: protein binding
Biological process: defense response to Gram-negative bacterium; defense response to Gram-positive bacterium; killing of cells of another organism; epidermis development
Genetic constraint (gnomAD): Loss-of-function variants: 0 observed, 0.35 expected, observed/expected ratio (o/e) 0, 90% interval 0 to 1.86. That is too few expected variants to judge how well the gene tolerates losing a copy. Missense variants: 130 observed, 121.67 expected, observed/expected ratio (o/e) 1.07, 90% interval 0.93 to 1.24. Synonymous variants: 46 observed, 45.88 expected, observed/expected ratio (o/e) 1, 90% interval 0.79 to 1.28.
Homologues: Orthologues: chimpanzee LCE3A (96% identical), rabbit LCE3A (79% identical). Paralogues in human: LCE3C (82% identical), LCE3B (81% identical), LCE3D (81% identical), LCE3E (79% identical), LCE5A (63% identical), LCE1E (62% identical), LCE2D (62% identical), LCE1F (61% identical), LCE2C (61% identical), LCE2A (60% identical), LCE2B (60% identical), LCE1D (57% identical), and 8 more.
Diseases named in the same sentence as LCE3A in open-access papers:
LCE3A is named in the same sentence as 6 diseases in open-access papers, as found by Europe PMC text mining. Sharing a sentence is not in itself a finding about the gene and the disease. The quoted sentences say what the papers report.
psoriasis (7 papers, 2016 to 2024). An autoimmune condition characterized by red, well-delineated plaques with silvery scales that are usually on the extensor surfaces and scalp. "Previous studies have reported a strong association between the severity of psoriasis and the Lce3a and Lce3d locus." (PMID 37465147, 2023). "In lesional psoriasis skin, the expression of LCE3A, LCE3B and LCE3C is markedly increased, which is consistent with our findings." (PMID 34440590, 2021). "We observed highly variable expression pattern of LCE3A gene in the involved skin of psoriasis patients in comparison to the uninvolved skin." (PMID 27048876, 2016). "In psoriasis patients, the majority of whom harbor genomic deletion of LCE3B and LCE3C (LCE3C_LCE3B-del), we propose that certain dietary analogues of 1,25D activate the expression of residual LCE3A/LCE3D/LCE3E genes to compensate for the loss of LCE3B/LCE3C in the deletant genotype." (PMID 29401702, 2018). "Considering these observations, we can speculate that in psoriasis patients with LCE3C-3B deletion, LCE3A gene is upregulated to compensate the barrier repair function of LCE3C-3B genes." (PMID 27048876, 2016).
eczema (1 paper, 2023). "Notably, AMPs such as PI3 or LCE3A are also downregulated, while DCD, an antimicrobial component of sweat typically downregulated in eczema, shows the opposite direction." (PMID 37298605, 2023).
LCE3A also shares sentences with these, for which no sentence is quoted: cancer (1 paper); oral cancer (1); prostate carcinoma (1); tumor (1).